SLC25A35 (solute carrier family 25 member 35)
Description:
Putative antiporter that exchanges dicarboxylates and sulfur oxoanions across the inner membrane of mitochondria.
Synonyms: FLJ40217
Tractability: Antibody: UniProt predicts a signal peptide or a membrane-spanning region.
Gene: Protein-coding gene on chromosome 17 (8,287,763 to 8,295,410, reverse strand). Ensembl gene ENSG00000125434.
Subcellular location: Mitochondrion inner membrane
Subcellular location (Human Protein Atlas): Mitochondria; Vesicles
Gene Ontology:
Molecular function: phosphoenolpyruvate transmembrane transporter activity
Biological process: glycerol-3-phosphate biosynthetic process; phosphoenolpyruvate transmembrane transport
Cellular component: mitochondrion; mitochondrial inner membrane
Genetic constraint (gnomAD): Loss-of-function variants: 32 observed, 32.27 expected, observed/expected ratio (o/e) 0.99, 90% interval 0.75 to 1.33. The upper end of that interval is the gene's LOEUF score, 1.33, which puts it in group 5 of 6, group 1 being the genes least tolerant of losing a copy. Missense variants: 369 observed, 405.21 expected, observed/expected ratio (o/e) 0.91, 90% interval 0.83 to 0.99. Synonymous variants: 142 observed, 165.63 expected, observed/expected ratio (o/e) 0.86, 90% interval 0.75 to 0.99.
Homologues: Orthologues: chimpanzee SLC25A35 (99% identical), macaque SLC25A35 (99% identical), pig SLC25A35 (94% identical), dog SLC25A35 (93% identical), guinea pig SLC25A35 (92% identical), mouse Slc25a35 (91% identical), rabbit SLC25A35 (78% identical), rat Slc25a35 (78% identical), zebrafish slc25a35 (62% identical). Paralogues in human: SLC25A34 (50% identical), SLC25A30 (29% identical), SLC25A14 (28% identical), UCP3 (27% identical), SLC25A29 (26% identical), UCP2 (26% identical), SLC25A21 (25% identical), SLC25A48 (25% identical), UCP1 (25% identical), SLC25A12 (25% identical), SLC25A13 (25% identical), SLC25A27 (25% identical), and 37 more.
Diseases named in the same sentence as SLC25A35 in open-access papers:
SLC25A35 is named in the same sentence as 7 diseases in open-access papers, as found by Europe PMC text mining. Sharing a sentence is not in itself a finding about the gene and the disease. The quoted sentences say what the papers report.
Hepatic steatosis (1 paper, 2025). Steatosis is a term used to denote lipid accumulation within hepatocytes. "Together, this study offers SLC25A35 as a promising target to selectively limit excess fatty acid esterification and triglyceride synthesis, which are hallmarks of hepatic steatosis and insulin resistance." (PMID 41446167, 2025). "Lastly, we explored the therapeutic potential of blocking SLC25A35-mediated lipogenesis by determining the extent to which inducible depletion of SLC25A35 in obese mice ameliorates hepatic steatosis." (PMID 41446167, 2025). "Together, SLC25A35 blockade in the liver by two complementary approaches, Alb-Cre–mediated deletion and AAV-Cre–induced depletion, effectively ameliorated obesity-associated hepatic steatosis in vivo." (PMID 41446167, 2025). "Furthermore, blockade of SLC25A35 in the liver of obese mice markedly decreased glycerolipid accumulation, ameliorated hepatic steatosis, and improved systemic glucose homeostasis." (PMID 41446167, 2025). "Hence, we examined the extent to which liver-specific blockade of SLC25A35 prevents the pathogenesis of diet-induced hepatic steatosis." (PMID 41446167, 2025). "Significantly, inducible depletion of SLC25A35 effectively alleviated hepatic steatosis without inducing liver damage." (PMID 41446167, 2025).
Insulin resistance (1 paper, 2025). Increased resistance towards insulin, that is, diminished effectiveness of insulin in reducing blood glucose levels. "Thus, we next determined the extent to which liver-specific deletion of SLC25A35 protects mice from diet-induced insulin resistance." (PMID 41446167, 2025).
SLC25A35 also shares sentences with these, for which no sentence is quoted: Anxiety (1 paper); breast tumor (1); endometrial cancer (1); Obesity (1); Type 2 diabetes (1).